SPATC1L (spermatogenesis and centriole associated 1 like)
Synonyms: C21orf56
Tractability: Antibody: the Human Protein Atlas places it where antibodies can reach. PROTAC: ubiquitination databases record sites on it.
Gene: Protein-coding gene on chromosome 21 (46,161,148 to 46,184,476, reverse strand). Ensembl gene ENSG00000160284.
Subcellular location: Cytoplasm
Subcellular location (Human Protein Atlas): Cytosol; Plasma membrane
Gene Ontology:
Molecular function: protein binding; protein kinase A regulatory subunit binding
Biological process: spermatogenesis
Cellular component: cytoplasm; centrosome; sperm head-tail coupling apparatus
Genetic constraint (gnomAD): Loss-of-function variants: 25 observed, 19 expected, observed/expected ratio (o/e) 1.32, 90% interval 0.96 to 1.79. The synonymous counts are far from expectation, so gnomAD's model fits this gene poorly and the ratio says little. Missense variants: 499 observed, 442.81 expected, observed/expected ratio (o/e) 1.13, 90% interval 1.05 to 1.21. Synonymous variants: 290 observed, 212.84 expected, observed/expected ratio (o/e) 1.36, 90% interval 1.24 to 1.5.
Homologues: Orthologues: chimpanzee SPATC1L (97% identical), macaque SPATC1L (97% identical), mouse Spatc1l (85% identical), guinea pig SPATC1L (84% identical), pig SPATC1L (84% identical), dog SPATC1L (80% identical). Paralogues in human: SPATC1 (34% identical).
Diseases named in the same sentence as SPATC1L in open-access papers:
SPATC1L is named in the same sentence as 11 diseases in open-access papers, as found by Europe PMC text mining. Sharing a sentence is not in itself a finding about the gene and the disease. The quoted sentences say what the papers report.
acephalic spermatozoa syndrome (1 paper, 2021). "The deletion of Spatc1l (spermatogenesis and centriole-associated 1 like) alters the sperm head-tail integrity and causes acephalic spermatozoa syndrome in mice." (PMID 34422805, 2021).
Alzheimer disease (1 paper, 2019). A progressive, neurodegenerative disease characterized by loss of function and death of nerve cells in several areas of the brain leading to loss of cognitive function such as memory and language. "Recent reports highlight several examples, including SPATC1L in male infertility, PM20D1 in Alzheimer’s disease, and DUSP22 in lymphoma." (PMID 31155008, 2019).
cancer (2 papers, 2018 to 2022). A tumor composed of atypical neoplastic, often pleomorphic cells that invade other tissues. "Remarkably, at seven of these, peripheral blood DNA methylation at baseline was significantly associated with later cancer; three (SPATC1L, VTRNA2-1, and DUSP22) were significantly associated with multiple types of cancer." (PMID 29310692, 2018). "Methylation at three clusters (SPATC1L, VTRNA2-1, and DUSP22) showed significant associations with two types of cancer." (PMID 29310692, 2018).
SPATC1L also shares sentences with these, for which no sentence is quoted: acute myeloid leukemia (1 paper); age (1); B-cell neoplasm (1); hearing loss (1); Infertility (1); lung carcinoma (1); lymphoma (1); male infertility (1).